MIR1233-1 (microRNA 1233-1)
Synonyms: hsa-mir-1233; MIR1233; MIRN1233; hsa-mir-1233-1
Gene: MicroRNA gene on chromosome 15 (34,382,069 to 34,382,150, reverse strand). Ensembl gene ENSG00000221649.
Homologues: Paralogues in human: MIR1233-2 (100% identical).